IL6 (interleukin 6)
Diseases named in the same sentence as IL6 in open-access papers (continued):
Sharing a sentence is not in itself a finding about the gene and the disease.
diabetes (continued). "We included the following factors in the logistic regression model as important: Gender, Hypertension, AKI, Treatment with Remdesivir, Febrile, CKD, age, IL-6, CRP, uNGAL, uKIM-1, Diabetes, and Proteinuria." (PMID 36983566, 2023). "Diabetes augments levels of inflammatory cytokines such as TNF-α, interleukin-1β (IL-1β), interleukin-17 (IL-17), interleukin-23 (IL-23), and interleukin-6 (IL-6) in human periodontal tissue." (PMID 36875028, 2023). "Metformin, as a well-known drug for diabetes, can inhibit SASP by decreasing the expression of IL-1β, IL-6, C-X-C motif chemokine 5 (CXCL5) and NF-kB." (PMID 36744145, 2023). "Among subjects with diabetes, those with TIR ≤ 70% had higher levels of IL-1α, IL-1β, IL-6, IL-12 p70, IL-16, LIF, M-CSF, MCP-1, MCP-3, RANTES, TNF-α, TNF-β, and b-NGF, and lower levels of IL-1α, IL-4, IL-10, GM-CSF, and MIF than individuals with TIR > 70%." (PMID 37893217, 2023). "Diabetes mellitus, increased levels of CRP, and ferritin were identified as the most significant predictors of poor outcomes in contrast to increased levels of IL-6." (PMID 38034537, 2023). "CAD: coronary artery disease; CRP: c-reactive protein; IL6: interleukin 6; MDA: malondialdehyde; T2DM: type 2 diabetes mellitus; TAC: total antioxidant capacity; TNF-α: tumor necrosis factor-alpha." (PMID 38034261, 2023). "CRP: c-reactive protein; IL6: interleukin 6; MDA: malondialdehyde; SUA: serum uric acid; T2DM: type 2 diabetes mellitus; TAC: total antioxidant capacity; TNF-α: tumor necrosis factor-alpha." (PMID 38034261, 2023). "In diabetes, proinflammatory cytokines, such as TNF-α, IL-1, and IL-6, activate inflammatory signaling pathways, which lead to cardiac fibrosis, hypertrophy, cell death, systolic and diastolic dysfunction, and finally heart failure." (PMID 38069059, 2023). "In diabetes, IRF7 knockdown increases anti-inflammatory IL-10 production and decreases proinflammatory IL-6 level in bone marrow-derived macrophages." (PMID 36336986, 2023). "MSCs that have been exposed to hypoxia express higher levels of VEGF, IL-6, MCP1, and MMP9.These hypoxia-treated MSCs increased islet grafts in a model of streptozotocin-induced diabetes in mice with lowering of the blood glucose level." (PMID 37761001, 2023). "Many studies have reported the efficacy of moringa and ginger in type 2 diabetes mellitus, neurodegenerative disease, cardiovascular disease, cancer, and kidney disease by reducing inflammatory cytokines activities, mainly of TNF-α and IL-6." (PMID 37570837, 2023). "It has been demonstrated that patients with diabetes tend to have a higher level of inflammatory cytokines, such as tumor necrosis factor α (TNF-α) and interleukin (IL-6)." (PMID 35631151, 2022). "We showed that patients on therapy with SGLT-2i have lower circulating levels of IL-6, a prototypical marker of LGI with a recognised prognostic value for the development of diabetes complications." (PMID 35503137, 2022). "Decreased muscle strength is related to increased levels of inflammatory markers (tumour necrosis factor-alpha (TNF-α), interleukin-6 (IL-6), and C-reactive protein (CRP)), which can induce the development of diabetes." (PMID 36010223, 2022). "Many studies have demonstrated that diabetes can increase the levels of human pro-inflammatory factors, such as TNF-α, IL-1β, and IL-6." (PMID 35813617, 2022). "Age, sex, educational history, body mass index, medical condition (hypertension, heart disease, diabetes mellitus),C‐reactive protein (CRP), interleukin‐6 (IL‐6) and physical activity (light, moderate–vigorous)." (PMID 34997702, 2022). "Rather, sustained STING expression in diabetes is detrimental to wound healing due to decreased Mφ-mediated IFN-I production and increased IL-1β, TNF-α, and IL-6 production, all of which act in concert to sustain a proinflammatory Mφ phenotype." (PMID 36127466, 2022). "In diabetes mellitus, TPRG1L was upregulated compared with in normal people and activated the NF-κB/IL-6 axis." (PMID 36401185, 2022).
diabetes (continued). "Treatment of valproic acid for 8 weeks significantly attenuated diabetes-induced expression of p21 and the SASP markers Il-6, TNF-α, EGFR and Fn." (PMID 36434087, 2022). "Several pro-inflammatory markers, such as C-reactive protein, IL-1b, IL-6, IL-8, and TNF-α, are elevated in migraine and diabetes." (PMID 36498528, 2022). "There are mechanistic links between periodontitis and other metabolic diseases, namely diabetes, which results in the production of inflammatory cytokines such as IL-1β, TNF, IL-6, as well as oxidative stress." (PMID 36013449, 2022). "SGLT-2 inhibitors can reduce inflammatory markers such as interleukin-6 (IL-6), monocyte chemoattractant protein-1 (MCP-1), and tumor necrosis factor (TNF-α), thereby alleviating arteriosclerosis in diabetes animal models." (PMID 35676606, 2022). "Diabetes triggered NLRP3, ASC, gasdermin-N, caspase-1, and collagen I expression in myocardial tissue, and promoted an increase in the serum TNF-α, IL-1β, IL-6, and IL-18 levels." (PMID 36320147, 2022). "In another ex vivo study, the number of osteoclasts expressing IL-6 and TNF-α was elevated in bone specimens from diabetes patients suffering from CN." (PMID 36499493, 2022). "A high concentration of IL-6 and a combined increase of IL-6 and IL-1b, both SASP factors, are independent predictors of diabetes." (PMID 35204091, 2022). "Next to a reduction of IL-6 serum levels it has been reported that phosphodiesterase-5 inhibitors like sildenafil also reduce MCP-1 levels in men with diabetes and affect circulating monocytes and tissue inflammatory cell infiltration." (PMID 36209229, 2022). "At present, CRP, IL-6, and TNF-α are recognized as representative markers of inflammatory factors in patients with diabetes, which can damage EPCs’ function, and reduce endothelial regeneration and vascular repair." (PMID 36199064, 2022). "We observed that pro-inflammatory cytokines such as TNF-α, IL-6, and IL-1β were increased following HFD-induced diabetes." (PMID 35928902, 2022). "The increasing IL-6, IL-1α, TNF-α and TGF-β expression in the lungs of diabetic rats indicates that the expression of proinflammatory cytokines was upregulated in diabetes and was downregulated by insulin and Rb1 treatment." (PMID 36367996, 2022). "Compared with previous studies, we evaluated immunologic indices, including IL-6, TNF-α, IL-4, IL-10, TGF-β1 levels, and regulatory T cells, in addition to general diabetes evaluation." (PMID 35725652, 2022). "TF Rfx1is playing downstream role on signal transducer and activator of transcription 3 (STAT3) pathway while the expression of Rfx1 is regulated by interleukin-6 (IL-6)-STAT3 signaling pathway, and STAT3 plays an important role in diabetes pathogenesis." (PMID 36037214, 2022). "With the progression of the disease, the mRNA expression levels of IL-6, ICAM, and TNF-α were in a high expression state in the diabetes group, and a new peak appeared at the 10th week." (PMID 35126785, 2022). "A report has indicated that the overexpression of miR-342-3p following inhibition of NEAT1 decreases the release of the inflammatory cytokines IL-6, IL-1β, TNF-α, and cyclooxygenase-2 in type 1 diabetes mellitus." (PMID 36310619, 2022). "• Inhibition of adipocyte differentiation. • Increase of inflammatory molecules like COX2 and PEG2. • Induction of IL6 synthesis by adipocytes. • CDK5-dependent phosphorylation of PPARγ in adipocytes, favoring gene expression related to diabetes." (PMID 35422689, 2022). "AKT1, VEGFA and IL-6, as enriched targets or downstream key factors of the PI3K-AKT pathway, are relevant factors in the pathogenesis of diabetes." (PMID 36559019, 2022). "ROC curve analysis showed that the AUC of CD3+ T cells and that of IL-6 were 0.806 and 0.785, respectively, and the AUC of combined predictor (combining age, diabetes mellitus, CD3+ T cell count reduction, and IL-6 elevation) was 0.887." (PMID 35346253, 2022).
diabetes (continued). "Diabetes induced the upregulation of serum TNF-α, IL-6, and IL-1β, and treatment with anti-ANGPTL3/IL22 showed prominent reversal compared with mIL22Fc or anti-ANGPTL3 alone." (PMID 36544775, 2022). "Diabetes induction resulted in an increase in proinflammatory parameters TNF-α, IL-1β and IL-6, which were estimated using an ELISA technique in this study." (PMID 35335923, 2022). "Previous reports indicated that persistent hyperglycemia was closely associated with a pro-inflammatory status, characterised by a significant elevation of IL-1β, IL-6, -1B and -8 and TNF-α in patients with uncontrolled diabetes and ketoacidosis." (PMID 35327652, 2022). "It was proposed that the influence of COVID-19 infection was amplified by DPP4 in patients with diabetes, and through its interaction with INS, leptin, IL-6 and other proteins." (PMID 34996987, 2022). "It was found that age, diabetes mellitus, CD3+ T cells < 510.50 × 106/L on hospital admission, and IL-6 > 6.58 pg/mL on hospital admission were the predictive factors for the development of severe disease." (PMID 35346253, 2022). "Studies were selected if sedentary behaviour and physical activity were measured by accelerometer in the general population, and if associations were reported with glucose, insulin, HOMA-IR, insulin sensitivity, HbA1c, diabetes incidence, CRP and IL-6." (PMID 35544519, 2022). "The FPG, 2hPG, HbA1C, CRP, IL-6, Visfatin, JAZF1, HOMA-IR, EAT thickness, and baPWV of the Complication Group were all higher than those of the Diabetes Group and the Healthy Control Group (P < 0.05, respectively)." (PMID 33722242, 2021). "In the comparison between diabetes and diabetes + ABS, the first IL-6 levels were significantly lower in the ABS group." (PMID 33244945, 2021). "The FPG, 2hPG, TG, HbA1C, CRP, IL-6, visfatin, JAZF1, HOMA-IR, baPWV, and EAT thickness of the Diabetes Group were all higher than those of the Healthy Control Group, with statistical significance (P < 0.05)." (PMID 33722242, 2021). "More specifically, NF-κB has been found to be a key regulator in the crosstalk between diabetes, inflammation and CRC through the upregulation of IL-6, IL-1 α and TNF α." (PMID 34842660, 2021). "In our current findings, we discovered that the AhR agonist VAF347 not only inhibited diabetes-mediated VEGF and retinal inflammation, but also systemically ablated hyperglycemic induced IL-6 production." (PMID 33919327, 2021). "The Nrf2 activator dh404 prevented an increase in diabetes-induced inflammatory mediators, including TNF-α, IL-6, ICAM-1, and MCP-1, in Müller cells." (PMID 34938383, 2021). "Diabetes significantly triggered the increases of pro-inflammatory cytokines (TNF-α and IL-6) and decrease of the anti-inflammatory cytokines (IL-10)." (PMID 34497508, 2021). "Similarly, in a “diabetes-like” condition, the phosphomimetic (148D) HspB4/αA-crystallin mutant had an even greater dampening effect than that of the WT HspB4/αA-crystallin as demonstrated by a greater decrease in the induction of IL-6 (78%), IL-1β (79%), and MCP-1 (83%)." (PMID 34071438, 2021). "Diabetic ischemic ulcer granulation tissue exhibited the largest concentrations of MDA, IL-6, and AGEs as compared to the relevant healthy donor-control granulation tissue." (PMID 36994347, 2021). "The reverse was the case for hepatic IL-6 and TNF-α, as diabetes onset significantly (p < 0.05) increased the expression of these genes by 228.0 and 95.1%, respectively." (PMID 34956587, 2021). "Treatment with Tocilizumab was initiated in 349 patients (9%) with severe evolution, of which 103 (29.5%) with diabetes mellitus selected on the basis of severity criteria: sudden desaturation, increased CRP, ferritin, D-dimers, LDH, and interleukin 6 values." (PMID 34201473, 2021).
diabetes (continued). "Furthermore, IL-6 is a pro-inflammatory cytokine that triggers host defense by sending out inflammatory signals when microbial infections or tissue damage occur, while the persistence of IL-6 could stimulate the onset of inflammatory and autoimmune diseases such as diabetes and RA." (PMID 34966780, 2021). "The rationale of choosing this biomarker as a leading factor for investigation among other candidates is that IL-6 and tumor necrosis factor-alpha (TNF-α) appear to have the highest impact on the promotion of CAD in patients with diabetes mellitus." (PMID 34193056, 2021). "Various studies have reported that increased expression of inflammatory markers such as IL-6, IL-1β, and MCP-1 inactivated retinal MGCs due to diabetes-induced stress." (PMID 34071438, 2021). "The major finding of this study was that rats with diabetes in the ECMO model showed rapidly increased inflammatory cytokines, such as TNF-α and IL-6, and other measurements, such as AST, ALT, LDH and L-FABP." (PMID 33920465, 2021). "Estrogen has been found to suppress the production of inflammatory mediators, such as IL-1, IL-6 and TNF-α, and these parameters are reported to play a decisive role in the pathogenesis of diabetes mellitus." (PMID 34746187, 2021). "In response to injury, M1 phenotype macrophages release IL-6 and TNF-α, and in Type 2 diabetes mellitus, levels of these cytokines are elevated." (PMID 33628374, 2021). "Wang, Z found that the inflammatory response related proteins were significantly increased in the brain with diabetes, including tumor necrosis factor-α (TNF-α), NF-κB, cyclooxygenase-2 (Cox-2) and interleukin-6 (IL-6)." (PMID 33602334, 2021). "The observed increase in the concentration of these inflammatory mediators (IL-6 and TNF-α) after diabetes induction in rats was suppressed by TCA treatment, suggesting the anti-inflammatory effect of TCA in diabetic rats." (PMID 34956587, 2021). "Moreover, chronic inflammation associated with diabetes favors carcinogenesis, malignant transformation, tumor growth, invasion and metastasis through the action of proinflammatory cytokines, such as tumor necrosis factor-alpha (TNF-α) and interleukin-6 (Il-6)." (PMID 33922197, 2021). "Recent work further identified that CXCL13/CXCR5 contributes to diabetes-induced mechanical hypersensitivities by activating pERK, pSTAT3, and pAKT pathways and promoting TNF-α and IL-6 production in SCDH." (PMID 33602238, 2021). "We also found that diabetes was related to increased expression of nine proteins, IL-18R1, CCL11, CDCP1, OPG, HGF, TGF-α, CCL20, IL-6 and FGF-21." (PMID 34385358, 2021). "Other studies suggest a link between elevated levels of IL-6 and AMPK/mTOR signaling pathway and their role in exacerbating diabetes-induced complications and insulin resistance." (PMID 34367059, 2021). "MNCs were isolated from 50 mL of peripheral blood of patients with diabetes mellitus and healthy volunteers (n = 13 each) and subjected to QQc for 7 days in serum‐free expansion media with VEGF, Flt‐3 ligand, TPO, IL‐6, and SCF." (PMID 33599112, 2021). "Thirdly, studies demonstrated that the oxidative stress induced by diabetes increased proinflammatory factors such as the level of TNF-α and IL-6 and raised inflammatory molecules like vascular cell adhesion molecule 1 (VCAM1)." (PMID 33456672, 2020). "In this case report, we described for the first time the differential expression of TNF-α, IL-1β, IL-6, and IFN-γ in a blood sample that was taken from a 27-year-old patient with type 1 diabetes mellitus (T1DM) who was diagnosed with HU." (PMID 33375551, 2020).
diabetes (continued). "Interleukin (IL)-6 is implicated in both the pathogenesis of RA and in glucose homeostasis; this post hoc analysis investigated the effects of IL-6 receptor vs. tumour necrosis factor inhibition on glycosylated haemoglobin (HbA1c) in patients with RA with or without diabetes." (PMID 32907617, 2020). "The frequency of severe cases was higher in diabetes patients that showed higher concentrations of C-reactive protein (CRP), lactate dehydrogenase (LDH) and IL-6, lower CD4/CD8 cell ratio compared to other two groups." (PMID 33584667, 2020). "Importantly, INU treatment could decrease TNF-α and IL-6 but increase IL-10 in diabetes mice." (PMID 33390939, 2020). "In a model of streptozotocin-induced diabetes in Sprague–Dawley rats, bFGF delayed the progression of diabetic nephropathy, possibly by inhibiting NF-κB and silencing of TGF-β1, MCP-1, IL-6, and IL-1β." (PMID 32961903, 2020). "Neurological degeneration was also significantly improved, accompanied by decreased levels of inflammatory factors (TNF‐α, 57.8%; IL‐1β, 51.4%; IL‐6, 62.8%; and MDA, 40.7% reduction rate against the diabetes mellitus + normal saline group)." (PMID 33215875, 2020). "We show that diabetes leads to higher systemic levels of LTB4, IL-6 and TNF-α in cutaneous leishmaniasis." (PMID 32525457, 2020). "The increased risk of carotid abnormalities attributable to anti-GRP78 autoreactivity persisted despite adjustment for age, smoking extent, hypertension, diabetes, hyperlipidemia, or levels of CRP, IL-6, and TNF-α." (PMID 32086320, 2020). "Interleukin-6 is another key player in ICI-induced cardiotoxicity; it is an independent predictor of diabetes and cardiovascular diseases." (PMID 33096896, 2020). "In an alternative streptozotocin-induced diabetes model, elevated levels of GSK3β were accompanied with increased TNF, IL-1β, and IL-6 levels in the hippocampus." (PMID 32231133, 2020). "Eight weeks CS or metformin administration decreased IL-1β, IL-6 and TNF-α levels (CS vs. diabetes, p < 0.01, Met vs. diabetes, p < 0.01)." (PMID 32722636, 2020). "To investigate the role of Ufm1 in diabetes mice, we first analyzed the expression of Ufm1 and proinflammation cytokines (TNF-α, IL-6, and IL-1β) in db/db mice." (PMID 31829413, 2020). "Similar results were observed when we replaced diabetes with inflammatory markers (i.e., C-reactive protein [CRP], tumor necrosis factor alpha [TNF-α], interleukin-6 [IL-6], and monocyte chemoattractant protein-1 [MCP-1]) or serum albumin concentration." (PMID 32661200, 2020). "In the stepwise analysis, covariant factors included hypertension, diabetes mellitus, hs-CRP, LDL-C, smoking, triglycerides, WBC, and IL-6." (PMID 32652935, 2020). "After 6 weeks of diabetes, the levels of Scr, BUN, TG, HDL-C, and IL-6 were significantly increased in STZ group compared with the ND group." (PMID 32660472, 2020). "IL-6 is the most commonly elevated cytokine in cytokine storms from conditions involving chronic micro-inflammation, such as CVD, diabetes and CKD." (PMID 32733487, 2020). "Induction of diabetes in old rats resulted in significant increase in SBP, aortic PWV, renal artery resistance, and serum levels of ET1, ANG II, IL-6, TNF-α, MDA, ROS, and VEGF." (PMID 32426041, 2020). "Administering ALA for 4 months to patients with type 2 diabetes mellitus on the background of basic therapy contributes to a significant reduction in CRP by 30.9%, IL-6 by 29.7%, and TNF-α by 22.7%." (PMID 32341698, 2020). "A review by Singh & Newman concludes that, of the inflammatory markers examined in cohort studies of aging, IL-6 is most robustly related to multiple disease outcomes, including CVD, diabetes, cancer, as well as disability and mortality." (PMID 31367727, 2019). "Regarding the mechanisms involved in the beneficial effect of the SOCS1 peptidomimetic, we found that it reduces the upregulation of IL-1β, IL-6, TNF-α, and VEGF induced by diabetes." (PMID 31344857, 2019).